PSTK (phosphoseryl-tRNA kinase)
Description:
Specifically phosphorylates seryl-tRNA(Sec) to O-phosphoseryl-tRNA(Sec), an activated intermediate for selenocysteine biosynthesis. No activity with other tRNAs has been detected.
Synonyms: C10orf89; MGC35392
Tractability: PROTAC: ubiquitination databases record sites on it.
Gene: Protein-coding gene on chromosome 10 (122,954,381 to 122,997,513, forward strand). Ensembl gene ENSG00000179988.
Subcellular location (Human Protein Atlas): Actin filaments; Nuclear bodies; Nucleoli
Pathways (Reactome):
Metabolism: Selenocysteine synthesis
Gene Ontology:
Molecular function: kinase activity; L-seryl-tRNA(Sec) kinase activity; tRNA binding
Genetic constraint (gnomAD): Loss-of-function variants: 12 observed, 24.7 expected, observed/expected ratio (o/e) 0.49, 90% interval 0.31 to 0.79. The upper end of that interval is the gene's LOEUF score, 0.79, which puts it in group 3 of 6, group 1 being the genes least tolerant of losing a copy. Missense variants: 326 observed, 315.12 expected, observed/expected ratio (o/e) 1.03, 90% interval 0.94 to 1.13. Synonymous variants: 136 observed, 124.48 expected, observed/expected ratio (o/e) 1.09, 90% interval 0.95 to 1.26.
Homologues: Orthologues: chimpanzee PSTK (98% identical), dog PSTK (84% identical), pig PSTK (83% identical), mouse Pstk (76% identical), rat Pstk (74% identical), macaque PSTK (74% identical), guinea pig PSTK (65% identical), tropical clawed frog pstk (40% identical), Drosophila melanogaster Pstk (21% identical), Caenorhabditis elegans pstk-1 (18% identical).
Diseases named in the same sentence as PSTK in open-access papers:
PSTK is named in the same sentence as 8 diseases in open-access papers, as found by Europe PMC text mining. Sharing a sentence is not in itself a finding about the gene and the disease. The quoted sentences say what the papers report.
acute myeloid leukemia (1 paper, 2025). Acute myeloid leukemia (AML) is a group of neoplasms arising from precursor cells committed to the myeloid cell-line differentiation. "In acute myeloid leukemia (AML), inhibition of phosphoseryl-tRNA kinase (PSTK), a critical enzyme in selenoprotein biosynthesis, has been shown to selectively impair AML growth and eradicate chemoresistant leukemic stem cells while sparing normal hematopoietic cells." (PMID 40846966, 2025).
Cirrhosis (1 paper, 2022). A chronic disorder of the liver in which liver tissue becomes scarred and is partially replaced by regenerative nodules and fibrotic tissue resulting in loss of liver function. "In univariate analyses, both cirrhosis and GPC3 were identified as risk factors associated with HCC recurrence, whereas PSTK/GPX4 expression did not predict the prognosis of these HCC patients." (PMID 34983546, 2022).
endotoxemia (1 paper, 2020). "Knock-down studies of two of the factors required for Se processing that decrease after endotoxemia, selenophosphate synthetase 2 and phosphoseryl tRNA kinase, are reported to limit production of selenoproteins in vitro." (PMID 33224150, 2020).
cancer (2 papers, 2021 to 2022). A tumor composed of atypical neoplastic, often pleomorphic cells that invade other tissues. "We also recently showed that CRISPR disruption of selenocysteine biosynthesis machinery (SEPSECS, PSTK) hypersensitizes cancer cells against the lipid prooxidant tert-butyl hydroxide (TBH)." (PMID 33672555, 2021). "In a pan-cancer TCGA analysis, PSTK was also markedly upregulated in HCC." (PMID 34983546, 2022).
infection (1 paper, 2020). The state of being infected such as from the introduction of a foreign agent such as serum, vaccine, antigenic substance or organism. "Only PSTK was found to be highly secreted in the clearance stage compared to the infection stage and therefore was selected for further clinical validation with sera from several patients." (PMID 32298370, 2020). "It was found that only PSTK showed an increased level in the clearance stage compared to the infection stage." (PMID 32298370, 2020).
tumor (1 paper, 2022). "Analyses of the TCGA database indicated that PSTK is commonly upregulated in HCC patient tumor tissue samples as compared to normal control tissues, and patients with higher levels of PSTK expression exhibit a worse prognosis." (PMID 34983546, 2022). "We found that PSTK was significantly upregulated in HCC tumor tissue samples as compared to normal liver tissues in the TCGA database and in a cohort of HCC patient samples from our center." (PMID 34983546, 2022). "Immunohistochemical staining revealed that Punicalin treatment significantly downregulated GPX4, PSTK and Ki-67 activities in tumor samples." (PMID 34983546, 2022). "Consistent with PSTK knockout, Punicalin or Geraniin treatment induced significant decreases in GPX4 protein levels in these tumor cells." (PMID 34983546, 2022). "Analyses of data in The Human Protein Atlas further revealed that both PSTK and SOD2 were expressed at high levels in HCC relative to other tumor types." (PMID 34983546, 2022).
PSTK also shares sentences with these, for which no sentence is quoted: copy number variation (1 paper); hepatocellular carcinoma (1).